TNF (tumor necrosis factor)
Diseases named in the same sentence as TNF in open-access papers (continued):
Sharing a sentence is not in itself a finding about the gene and the disease.
cancer (continued). "Curcumin, an anti-inflammatory compound in turmeric, reduced TNF transcription in human cancer cells and lipopolysachharide (LPS)-stimulated murine microglia." (PMID 27487029, 2016). "IL-6 and TNFα are produced by the activated macrophages, a potential mechanism involved in cancer development." (PMID 26951793, 2016). "We previously identified key inflammatory pathways and NOTCH signalling in cancer promoting processes by Gene Set Enrichment Analysis (GSEA) using the high TNF network gene expression signature." (PMID 26871292, 2016). "Previous studies have revealed that proinflammatory factors, such as TNF-α, function as the key mediators of muscle atrophy in cancer cachexia." (PMID 27378829, 2016). "It has been shown that the EMT and cancer “stemness” properties, induced by TNF-α, are mediated by the upregulation Twist-1." (PMID 27429011, 2016). "It has been shown that cancer cells activate the secretion of several cytokines from liver tissue, including TNF-α, interleukin-1 and VEGF – factors that have also been implicated in the government of MSC migration." (PMID 27458162, 2016). "Tumor necrosis factor (TNF)-related apoptosis-inducing ligand (TRAIL) is a potent cancer cell-specific apoptosis-inducing cytokine with little toxicity to most normal cells." (PMID 27512955, 2016). "TNF-α has been found to closely interact with Notch signaling in regulating cancer development and metastasis." (PMID 27378829, 2016). "A number of recent studies have indicated TNFα has been found to be frequently upregulated and is important for inflammation-induced cancer through activating NF-κB." (PMID 27027438, 2016). "Important activators of STAT-3 include IL-6 and IL-11, which are often over-expressed in cancers, and inducers of NF-κB transcription include toll like receptor ligands, tumor necrosis factor alpha (TNF-α), and interleukin-1β." (PMID 27608848, 2016). "The classically activated MΦ1 phenotype, can be induced by interferon γ (IFNγ)/tumor necrosis factor α (TNFα) and exert a cytotoxic effect on cancer cells." (PMID 27231721, 2016). "Serial sections of a human cancer tissue array were stained simultaneously using anti-MUC16 or anti-TNFα or anti-IFNγ antibody." (PMID 26918940, 2016). "The ultimate goal for cancer immunological study is to achieve a treatment outcome where cancer-promoting cytokine signaling (TNFα, IL-1, IL-6, IL-17 and IL-23) is blocked to slow down cancer cell growth and reduce their survival and therapy resistance." (PMID 31051015, 2016). "Molecular dysregulation of TNF system was observed in cancer tissue by an increased number of TNF-α receptors and ligand-receptor activity." (PMID 27110571, 2016). "Cytokines secreted by inflammatory cells, including TNF-α, IL-1, and IL-6, play important roles in cancer-related inflammation." (PMID 26992854, 2016). "TNF-α activation can promote NF-ƙB to participate in development, survival, proliferation and metastases in cancer." (PMID 27609190, 2016). "Withanolides are also reported to have vital role against cancer and enhance the apoptosis in cancer cells as well as prevent tumorigenesis by inhibiting tumour necrosis factor-α (TNF-α) activated nuclear factor-κB (NF-κB)." (PMID 26831738, 2016). "First, we demonstrate that IFNα/Smac mimetic combination treatment is an effective strategy to induce cell death in TNFα- or TRAIL-responsive cancers by concomitant stimulation of both death receptor systems." (PMID 26788912, 2016). "The activation of NF-κB-mediated inflammation by extrinsic stimuli, such as TLR ligands, IL-1, and TNF-α, induces stemness in cancer cells." (PMID 28116318, 2016). "Under this framework, TNF-α was used as a model to investigate effects of chronic inflammation on cancer progression and the metabolic reprogramming involved in metastasis." (PMID 27379180, 2016). "Close correlation of TNF-α with Notch in the regulation of cancer development and metastasis has also been described." (PMID 27378829, 2016).
cancer (continued). "Tumor necrosis factor (TNF)-related apoptosis-inducing ligand (TRAIL) selectively targets cancer cells while sparing normal cells." (PMID 27626799, 2016). "Further, inactivation of GSK-3β can upregulate β-catenin during gastrin and TNF-α induced EMT of cancer cells." (PMID 27058759, 2016). "C/EBP β also induces MMP1/3 expression via the p38 mitogen-activated protein kinase (MAPK) pathway to mediate tumor necrosis factors (TNF)-α-induced cancer cell migration, contributing to the regulation of cancer metastasis." (PMID 27011164, 2016). "It is demonstrated that the multiple effects of TNF-α in cancers are due to the different downstream signaling pathways activated by the combination of TNF-α and its receptor (mainly through NF-κB and (or) AP-1 pathway)." (PMID 26992854, 2016). "Together, these data indicate a novel mechanism for TNF-α-independent TNFR2 agonism in cancer immunotherapy, and demonstrate the utility of target-agnostic screening in highlighting important targets during drug discovery." (PMID 27626702, 2016). "CD40 is a member of the tumor necrosis factor (TNF) superfamily that has attracted considerable interest in the field of immunotherapy of cancer due to its pivotal role in activation of dendritic cells (DCs) and stimulation of adaptive immunity." (PMID 27385210, 2016). "To date, the clinical use of TNFα has been limited to cancer treatment in the isolated limb perfusion (ILP) setting for soft tissue sarcoma and melanoma intrinsic metastases confined to the limb." (PMID 27342639, 2016). "Activation of NF-κB in immune cells results in the expression and production of multiple pro-inflammatory cytokines, including TNFα, IL-1, IL-6, IL-17 and IL-23, which promote cancer development in multiple mouse models." (PMID 31051015, 2016). "NK cells can secret TNF-α, a pro-inflammatory cytokine that can induce apoptosis of trophoblasts and cancer cells, and affect the remodeling of spiral arteries." (PMID 27765926, 2016). "Here, we demonstrated that probe-based confocal laser endomicroscopy (pCLE) can be used to track MSCs in vivo and individually monitor tumor necrosis factor (TNF)-related apoptosis-inducing ligand (TRAIL) gene expression within carcinomas." (PMID 27617958, 2016). "Luteolin has been shown to block Akt phosphorylation in TNF-α induced murine non-carcinoma intestinal epithelial cells." (PMID 26967558, 2016). "Depletion of CIP2A via siRNA in hepatocellular carcinoma, breast cancer and esophageal cancer not only decreased cancer cell proliferation but also sensitized cancer cells to chemotherapeutical agents like bortezomib and tumor necrosis factor." (PMID 26560124, 2015). "Taken together, our results identify a new RXRα antagonist with abilities to modulate TR3 functions indirectly by binding to RXRα and to convert TNFα signal to induce cancer cell apoptosis by targeting tRXRα." (PMID 26156677, 2015). "Despite concerns regarding a cancer inducing effect of anti-TNFα therapy, TNFα blockers have been previously considered as a therapeutic strategy for RCC." (PMID 26447542, 2015). "Prior to cancer diagnosis, two patients had been treated with cyclophosphamide, one with a tumor necrosis factor inhibitor, one with azathioprine, and three with mycophenolate mofetil." (PMID 25689302, 2015). "Intrathecal administration of 100 μg BE reversed the upregulation of IL-6 and TNF-α observed in the cancer group at the 2nd h after injection." (PMID 26649065, 2015). "The strong enrichment observed in LPS-stimulated cell extracts confirmed the functional role of HuR in the post-transcriptional control of TNF in human cancer cells (P < 0.001)." (PMID 26553968, 2015). "Tumor necrosis factor (TNF)-related apoptosis-inducing ligand (TRAIL) is a promising agent for cancer therapy." (PMID 25888191, 2015).
cancer (continued). "TNFα stimulation of cancer cells activates the caspase-dependent apoptotic pathway and the NFκB-dependent cell survival pathway that contributes to the chemoresistance or radiation-resistance of cancer cells." (PMID 25704885, 2015). "In contrast, not only have pro-tumourigenic effects of TNF-α been reported in various cancers e.g. breast, but interestingly, anti-TNF-α treatment of inflammatory diseases has led to a significant rise in the rates of malignancies in patients." (PMID 26407999, 2015). "It was shown that IWR-1 inhibited cell proliferation and EMT even in the presence of TNF-α-induced cancer cell stimulation." (PMID 26450645, 2015). "We have shown that IWR-1 significantly reduces the MMP2 and MMP9 activities in the cancer cells, even in the presence of TNF-α-induced cancer cell stimulation." (PMID 26450645, 2015). "Early in 1980 s, the genetic engineering products of TNF α have been used in the clinic treatment of cancers." (PMID 26337231, 2015). "A recent publication has clearly shown that through activation of TLR2 and TNF-alpha, versican can be accelerated to offer an appropriate environment for cancer cells to survive and pursue a metastatic spread." (PMID 25859560, 2015). "Serum TNF-α and IL-6 in the severe cancer group were higher than those in control, whereas serum IL-1β leveled off in all groups." (PMID 25797259, 2015). "Mechanistically, NIBP knockdown in cancer cells inhibited cytokine-induced activation of NFκB luciferase reporter, thus sensitizing the cells to TNFα-induced apoptosis." (PMID 25704885, 2015). "In this paper we provide evidence that anergized NK cells have the ability to induce differentiation of cancer stem cells and limit inflammation through the release of TNF-α and IFN-γ." (PMID 25860927, 2015). "We have previously demonstrated that, in mammalian cancer cell lines, TNF-α-induced NF-κB can increase HIF-1α mRNA, protein and activity levels, leading to transactivation of target genes in normoxia." (PMID 25510503, 2015). "It is particularly interesting that studies of pain in cancer patients have shown the importance of cytokine genes including IL6, TNF and IL1B polymorphisms." (PMID 26269716, 2015). "The perturbation in the network through overexpression of important regulatory proteins, such as FOS and TNF, determine the dynamic of the network and activate genes involved in different signaling pathways that play important roles in cancer." (PMID 26088082, 2015). "In fact, blockade of circulating TNF or inhibition of intrahypothalamic interleukin-1 receptors enhances food intake in animal models of cancer anorexia." (PMID 26504362, 2015). "For example, IL-1B secreted by activated macrophages has been shown to induce tumorigenic progression by increasing neovascu-larization, and TNF-alpha secreted by macrophages increased invasiveness of cancer cells via MMP-dependent mechanism." (PMID 27275223, 2015). "Recently, it was shown that TERT interact with NFκB and co-activate the expression of several genes, including cytokines, such as IL-6 and TNFα, that are critical for inflammatory reactions and cancer progression." (PMID 26298771, 2015). "It was shown that although TNF-α increased gelatin degradation by MMP2 and MMP9 in HCT116 cell supernatants, IWR-1significantly reduced the MMP2 and MMP9 activities in the cancer cells, even in the presence of TNF-α-induced cancer cell stimulation." (PMID 26450645, 2015). "Taken together, our results suggest that EBERs are instrumental for launching a vicious cancer-promoting inflammatory response represented by TNFα via TLR3 in vritro and in vivo." (PMID 26172457, 2015). "The role of the pro-inflammatory cytokines IL-2, IFN-γ and TNF in cancer is usually considered to be well-established." (PMID 26500775, 2015).
cancer (continued). "Many studies have demonstrated the involvement of the TNF-mediated apoptosis in cancer therapies such as ionizing radiation or the chemotherapeutic agent, daunorubicin." (PMID 25883971, 2015). "Here we describe NSC-640358 (N-6), a thiazolyl-pyrazole derived compound, acts as a selective RXRα ligand to promote TNFα-mediated apoptosis of cancer cell." (PMID 26156677, 2015). "These cells can be generated in the bone marrow in response to factors such as IL-6, GM-CSF, IL-1β, TNFα and have been shown to contribute to cancer immune evasion by suppressing T cell functions and promoting activation and expansion of Foxp3+ Tregs cells." (PMID 26109431, 2015). "TIMP3 is a recognized regulator of TNF bioavailability, and TNF signaling has the capacity to either drive or suppress cancer progression." (PMID 25807548, 2015). "The tumor necrosis factor (TNF) α protein plays a dual role in promoting and inhibiting cancer depending largely on the pathway initiated by the binding of the protein to its receptor." (PMID 25629232, 2015). "The complex role of Timp3 appears to be similar to the “double-edged sword” of TNF signaling in cancer." (PMID 25807548, 2015). "Given the overriding importance attributed to FOS and TNF in cancer biology and their high topological measures in the PPI network, we chose these genes to performed perturbation simulations of knockout and overexpression in the system." (PMID 26088082, 2015). "BMI influences cancers by releasing several inflammatory mediators, such as tumor necrosis factor alpha, interleukin-6, and prostaglandin E2." (PMID 25963193, 2015). "IL-1β and TNF-α are the most important inflammatory molecules involved in cancer-related inflammation." (PMID 26517517, 2015). "The FasL, TRAIL (TNF-related apoptosis-inducing ligand), and TNF-α death-inducing signaling pathways mediate mitotic catastrophe in these cancer cells through interactions of their ligands and receptors." (PMID 26569225, 2015). "Both the canonical and non-canonical NF-κB pathways have been reported to participate in autocrine production of TNFα in cancer cells." (PMID 25575821, 2015). "In general, various plant-derived polyphenols were shown to suppress TNF-α activated inflammatory pathways in both in vitro and in vivo models of cancer." (PMID 25665066, 2015). "Multiple cytokines have been documented to promote weight loss during either cancer or chronic infections including IL-1, IL-6, IFN-γ and TNF-α." (PMID 25769044, 2015). "Consistent with previous reports, significant upregulations of IL-1β, IL-6, and TNF-α mRNAs in the cancer group compared to the naive group were observed." (PMID 26649065, 2015). "On the other hand, neutrophilia was triggered by cancer-related inflammatory factors, including tumor necrosis factor-alpha, interleukin-6, granulocyte colony stimulating factor, and myeloid growth factors." (PMID 25885254, 2015). "Tumor necrosis factor (TNF), an anti-angiogenic agent in cancer treatment, is limitedto isolated limb perfusion due to systemic toxicities." (PMID 25897826, 2015). "NF-κB is a key player in mediating inflammatory responses and regulating key cytokines such as TNF-α, leading to cancer development." (PMID 25974126, 2015). "NF-κB, one of these DNA-binding proteins, has been identified as a potential molecular bridge between inflammation and cancer, and can induce proinflammatory cytokines such as IL-1, IL-6 and TNF-α." (PMID 25889203, 2015). "Chemotherapy is known to increase concentrations of proinflammatory cytokines such as TNF-α, IL-6, and IL-1β in cancer patients." (PMID 25945105, 2015). "TRAIL is a member of the tumor necrosis factor (TNF) superfamily and resistance is usually acquired by cancer tissue to prevent apoptosis and subsequent cell death." (PMID 27340608, 2015). "Given the results of other studies involving PolyIC-treated normal keratinocytes and different cancer types, one would expect that IFNβ and/or TNFα are needed for DC activation." (PMID 25888634, 2015).
cancer (continued). "There have been efforts to remove or kill cancer cells using microtubes functionalized with antibodies, selectin, and cancer-specific tumor necrosis factor (TNF)—related apoptosis inducing ligand (TRAIL) with a capture and a kill rate between 30–41%." (PMID 26011055, 2015). "The role of immunosuppression and/or anti-TNFα agents in relation to cancer development remains to be clarified as the literature reports contradictory results." (PMID 26447542, 2015). "Death signaling provided by tumor necrosis factor (TNF)-related apoptosis-inducing ligand (TRAIL) can induce death in cancer cells with little cytotoxicity to normal cells; this cell death has been thought to involve caspase-dependent apoptosis." (PMID 26000607, 2015). "CD8+ T lymphocytes are able to induce the death of cancer cells by cytolytic activity or secretion of effector cytokines such as IFN-γ or TNF-α." (PMID 25801067, 2015). "Tumor necrosis factor (TNF) is a cytokine produced by macrophages that can promote cancer cell death." (PMID 25972907, 2015). "Several well-established cachectic cytokines are elevated in the sera of cancer patients, including TNF-α, IL-6, and myostatin." (PMID 25972815, 2015). "Various initiating factors have been found to be involved in cancer-related inflammation such as nuclear factor κB (NF-κB), tumor necrosis factor-α (TNF-α), interleukin (IL)-1β, and IL-6." (PMID 26793111, 2015). "We also previously reported that NF-κBp65 gene expression is increased in the subcutaneous white adipose tissue of cachectic cancer patients, concomitantly to up-regulation of its inflammatory target genes IL-1β, TNF-α, CCL2/MCP-1, and IκB-α." (PMID 26732354, 2015). "As a major inflammatory cytokine, TNF has a paradoxical, context dependent impact on cancer progression." (PMID 25807548, 2015). "Similar results have been demonstrated in a human co-culture study in which cancer cells increased TNF-α expression in macrophages, thus inducing MMP expression and activity." (PMID 25588705, 2015). "RANKL, a TNFα family molecule, can also activate NF-κB signaling and transcriptionally regulate TNFα in osteoclasts and cancer cells." (PMID 26110849, 2015). "Overall, based on recent studies addressing the roles of TNF-α and IL-1β in malignancy, both cytokines are now considered potential targets for therapy in cancer." (PMID 25928089, 2015). "Together, our data illustrate a new RXRα ligand with a unique RXRα binding mode and the abilities to regulate TR3 activity indirectly and to induce TNFα-mediated cancer cell apoptosis by targeting RXRα/tRXRα." (PMID 26156677, 2015). "Previous studies have shown that bone marrow-derived MSCs inhibit effector T cell proliferation and IFNγ and TNFα expression and cytotoxicity against cancer cells." (PMID 25984529, 2015). "Another example is the stabilization of the positively charged tumor necrosis factor (TNF)-related apoptosis-inducing ligand (TRAIL) which displays high anti-cancer potency but a very short blood half-life of less than 30 minutes." (PMID 27182458, 2015). "NF-κB inhibition rescues the sensitivity to anti-cancer drug in chemoresistant cancer cells, through TNFα mediated apoptosis, and indeed increases tumor regression." (PMID 25686825, 2015). "Here, we present a new RXRα ligand with a distinct structure and an RXRα/tRXRα-dependent induction of cancer cell apoptosis with TNFα." (PMID 26156677, 2015). "TAMs release reactive oxygen species, tumor necrosis factor (TNF)-α, Interleukin [IL]-6 and IL-1β, promoting DNA damage, transformation and cancer cell survival." (PMID 25811194, 2015). "Taken together, we clearly demonstrated that IWR-1 significantly inhibited HCT116 and HT29 cell invasion and migration, even in the presence of TNF-α-induced cancer cell stimulation." (PMID 26450645, 2015). "Compared with the control group, TNF-α induced phosphorylation of IκBα in SGC7901 cancer cells in a time-dependent manner." (PMID 26696888, 2015).